SNX12 (sorting nexin 12)
Description:
May be involved in several stages of intracellular trafficking.
Tractability: Antibody: UniProt places it where antibodies can reach, with high confidence. PROTAC: ubiquitination databases record sites on it; its protein half-life has been measured.
Gene: Protein-coding gene on chromosome X (71,056,332 to 71,073,426, reverse strand). Ensembl gene ENSG00000147164.
Subcellular location: Membrane
Gene Ontology:
Molecular function: enzyme binding; phosphatidylinositol binding; protein binding; phosphatidylinositol-3-phosphate binding
Biological process: negative regulation of early endosome to late endosome transport; negative regulation of gene expression; negative regulation of protein catabolic process; negative regulation of protein processing; negative regulation of protein transport; regulation of endocytosis; endocytic recycling; late endosome to Golgi transport
Cellular component: early endosome; early endosome membrane; retromer complex; membrane
Homologues: Orthologues: mouse Snx12 (100% identical), chimpanzee SNX12 (99% identical), guinea pig SNX12 (99% identical), macaque SNX12 (99% identical), pig SNX12 (98% identical), rabbit SNX12 (98% identical), rat Snx12 (98% identical), tropical clawed frog snx12 (94% identical), zebrafish snx12 (91% identical), Drosophila melanogaster Snx3 (78% identical), Caenorhabditis elegans snx-3 (69% identical). Paralogues in human: SNX3 (78% identical), SNX1 (31% identical), SNX18 (31% identical), SNX2 (31% identical), SNX33 (31% identical), SNX4 (30% identical), SNX7 (29% identical), SNX11 (28% identical), SNX30 (27% identical), SNX8 (27% identical), SNX9 (27% identical), SNX10 (25% identical), and 3 more.
Diseases named in the same sentence as SNX12 in open-access papers:
SNX12 is named in the same sentence as 8 diseases in open-access papers, as found by Europe PMC text mining. Sharing a sentence is not in itself a finding about the gene and the disease. The quoted sentences say what the papers report.
Alzheimer disease (1 paper, 2024). A progressive, neurodegenerative disease characterized by loss of function and death of nerve cells in several areas of the brain leading to loss of cognitive function such as memory and language.
fragile X syndrome (1 paper, 2022). A genetic syndrome caused by mutations in the FMR1 gene which is responsible for the expression of the fragile X mental retardation 1 protein. "This set of genes included cancer oncogenes (CMYC, CKIT, BCL2, KRAS) and genes associated with different cancer types (ADAM12, ALOX5, SRSF6, VEGF12) as well as FMR1, associated with fragile X syndrome (OMIM: 300624), and SNX12, which is associated with neurodegenerative diseases." (PMID 35573091, 2022).
melanoma (1 paper, 2018). A malignant, usually aggressive tumor composed of atypical, neoplastic melanocytes. "Melanoma cells frequently exhibit phosphorylation of the corresponding serine of SNX12, SNX17, and SNX2137." (PMID 29520003, 2018).
neuroblastoma (1 paper, 2021). Neuroblastoma (NB) is the most common solid, extracranial childhood tumor. "Studies with the same neuroblastoma cells, and in rat primary cortical neurons, highlight that SNX12 expression increases as neurite outgrowth occurs and that SNX12 down-modulation attenuated its growth." (PMID 33931804, 2021).
cancer (2 papers, 2022 to 2025). A tumor composed of atypical neoplastic, often pleomorphic cells that invade other tissues. "Moreover, phosphorylation at corresponding sites in SNX1, SNX3, SNX12, and SNX17 has been reported in various cancer types, hinting at a potential link between SNX phosphorylation and disease states." (PMID 40349777, 2025).
SNX12 also shares sentences with these, for which no sentence is quoted: neurodegenerative disease (1 paper); Parkinson disease (1); tumor (1).